PAPPA2 (pappalysin 2)
Diseases named in the same sentence as PAPPA2 in open-access papers (continued):
Sharing a sentence is not in itself a finding about the gene and the disease.
tumor (11 papers, 2020 to 2026). "Mutations in the PAPPA2 have been associated with tumor progression and treatment of digestive tumors, although its role in CRC is not yet understood." (PMID 37214090, 2023). "Based on the TCGA database, the correlation of PAPPA2 mutation with tumour mutation burden, infiltrating immune cells and DNA damage repair was explored for further immunogenicity and anti‐tumour activity mechanisms." (PMID 35811392, 2022). "Our results demonstrated that patients with PAPPA2 mutation were associated with better clinical outcomes in ICIs treatment via activated immunogenicity and enhanced anti‐tumour immunity." (PMID 35811392, 2022). "A larger validation cohort of this rare tumor would be desirable to determine the applicability of findings to high risk disease and the true clinical diagnostic utility of PAPPA2." (PMID 36345344, 2022). "Moreover, TCGA‐LUAD tumours with PAPPA2 mutation had increased mRNA expression of DDR‐related genes." (PMID 35811392, 2022). "Moreover, PAPPA2 mutation was correlated with enhanced anti‐tumour immunity including higher activated CD4 memory T cells level, lower Treg cells level, and upregulated DNA damage repair pathways." (PMID 35811392, 2022). "From the single gene level, some of PAPPA2 mutations occurred only in responders and other mutations occurred only in non-responders, which demonstrated that even mutations of the same gene may play different roles in the tumor progression and treatment." (PMID 36139377, 2022). "Mutations within PAPPA2 have been associated with higher levels of CD4 memory cells and lower levels of Treg cells, suggestive that it limits tumor growth in humans." (PMID 40822650, 2025). "We utilized a multidimensional TCGA database to explore how PAPPA2‐Mut tumours respond to immunotherapy." (PMID 35811392, 2022). "PAPPA2‐Mut tumours were discovered with higher levels of TMB and NAL, which are associated with increased tumour immunogenicity." (PMID 35811392, 2022). "A comparing analysis in both TCGA‐LUAD and TCGA‐SKCM datasets showed that the PAPPA2‐Mut group had revealed higher activated CD4 memory T cells and lower Treg cells than PAPPA2‐WT tumours." (PMID 35811392, 2022). "GSEA of Reactome revealed that gene sets related to the DDR pathways (the nonhomologous end‐joining (NHEJ) pathway, homologous recombination repair (HR) pathway, etc.)were significantly enriched in PAPPA2‐Mut tumours (p < 0.001) in TCGA‐LUAD." (PMID 35811392, 2022). "We provide transcriptomic and protein expression evidence of a highly specific tumor marker, PAPPA2." (PMID 36345344, 2022). "Then RNA‐Seq data revealed that PAPPA2 mutation was significantly associated with higher activated CD4 memory T cells and lower Treg cells, suggesting an enhanced anti‐tumour immunity." (PMID 35811392, 2022). "Secreted PAPPA2 selectively cleaves IGFBPs in the stomach, resulting in altered IGF signaling and consequent alterations to important tumor-associated parameters such as cell migration." (PMID 32004755, 2020). "Hence, PAPPA2‐Mut tumours were correlated with increased immunogenicity and enhanced anti‐tumour immunity, implying a better performance in ICIs therapy." (PMID 35811392, 2022). "Moreover, PAPPA2‐Mut tumours were enriched with multiple DDR pathways, which are associated with the efficacy of ICIs treatment in tumours." (PMID 35811392, 2022). "Similarly, the TMB level was significantly higher in PAPPA2‐Mut tumours in the SKCM set (p < 0.001)." (PMID 35811392, 2022). "However, the understanding of the contribution of PAPPA2 mutation to the anti‐tumour immune system is still lacking and remains to be explored." (PMID 35811392, 2022). "Furthermore, we developed a prognostic nomogram based on IMPG2, BNC2, PAPPA2, ITGBL1and UNC13C expression levels in tumor cells to predict survival outcomes." (PMID 42157926, 2026).
tumor (continued). "The decreasing of free IGF‐1 levels led by dysfunction of PAPPA2 protein could result in an imbalanced growth hormone (GH)/IGF‐1 signalling pathway, which was related to DNA damage repair (DDR) pathway, immune system maintenance and anti‐tumour immune activation." (PMID 35811392, 2022).
cancer (5 papers, 2013 to 2024). A tumor composed of atypical neoplastic, often pleomorphic cells that invade other tissues. "We demonstrate that the ATM gene and the PAPPA2 gene could be identified as cancer prognosis related genes." (PMID 24069199, 2013).
genetic disorders (2 papers, 2015 to 2019). "PAPPA2, known as Pregnancy‐Associated Plasma Preproprotein‐A2, has long been used as a marker of foetal genetic disorders." (PMID 30945415, 2019). "PAPPA is well recognized as a marker for fetal genetic disorders and adverse pregnancy outcomes, however, there physiological role of PAPPA2 remains unclear." (PMID 26161641, 2015).
skeletal dysplasia (2 papers, 2019 to 2021). Any Mendelian diseases that affects growth and development of the skeleton. "PAPPA2 can play a role in normal development of children, and several rare dysfunctional mutations of PAPPA2, resulting in short stature and elevation of IGF1 levels as well as skeletal dysplasia, were reported in 2016." (PMID 34680885, 2021). "Importantly, skeletal phenotypes were described for Fam20c (non-lethal Raine syndrome), Lrrk1 (osteosclerotic metaphyseal dysplasia), Pappa2 (short stature), Sfrp4 (Pyle's disease), and Slc10a7 (skeletal dysplasia) prior to knowledge of the human skeletal dysplasias when mutated in humans." (PMID 32117046, 2019).
neurodevelopmental disorder (1 paper, 2025). A behavioral and cognitive disorder with onset during the developmental period that involves impaired or aberrant development of intellectual, motor, or social functions. "The strongest SNP associations were near genes previously identified for neuronal development and neurodevelopmental disorders, including PAPPA2 (rs147036913), SEMA6D (rs35175834), PDE4B (rs10789205), and CSMD1 (rs7830752)." (PMID 40490728, 2025).
PAPPA2 also shares sentences with these, for which no sentence is quoted: fetal growth restriction (5 papers); Growth failure (2); infection (2); inflammatory bowel disease (2); Ascites (1); digestive tumors (1); Down syndrome (1); Ewing sarcoma (1); Gastric Neuroendocrine Tumors (1); gastrointestinal disease (1); hereditary leiomyomatosis (1); Hyperglycemia (1); Hyperinsulinemia (1); Immunodeficiency (1); kidney cancer (1); leiomyoma (1); metabolic disease (1); metastatic disease (1); Onset (1); ovarian carcinoma (1); ovarian tumors (1); pituitary hormone deficiencies (1); placental insufficiency (1); pseudohypoparathyroidism (1); sexual precocity (1); skin cutaneous melanoma (1); systemic candidiasis (1); X-linked severe combined immunodeficiency (1).